S100A12 (S100 calcium binding protein A12)
Diseases named in the same sentence as S100A12 in open-access papers (continued):
Sharing a sentence is not in itself a finding about the gene and the disease.
Sepsis (continued). "In addition, elevated levels of S100A9 and S100A12 proteins in amniotic fluid are associated with elevated inflammatory markers in cord blood and an increased risk for early onset sepsis (EOS)." (PMID 32612607, 2020). "Among them, the neutrophil microbicidal peptides alpha defensins and the highly pro-inflammatory calgranulins proteins S100A8/A9 and S100A12 are now considered putative pathogenic factors in sepsis, cardiovascular diseases, rheumatoid arthritis or atherosclerosis." (PMID 20652028, 2010). "Experimental studies demonstrate that inhibition of S100A12 or blockade of its downstream signaling attenuates inflammation and tissue damage, whereas clinical evidence associates elevated circulating and urinary S100A12 levels with disease severity and adverse prognosis in sepsis." (PMID 41657733, 2026). "Firstly, although we observed a correlation between elevated S100A12 expression in serum and atrial tissue with increased susceptibility to new-onset AF in acute sepsis mice, we did not manipulate S100A12 gene to more definitively ascertain its relationship with new-onset AF in sepsis." (PMID 39444551, 2024). "This study aimed to investigate the association between plasma S100A12 levels and the risk of SA-AKI in a prospective sepsis cohort." (PMID 41572197, 2026). "Elevated levels of S100A8 and S100A12 are considered a potential biomarker of sepsis in human patients, and their levels of expression have been associated with poor disease outcomes." (PMID 40599378, 2025). "The results showed that S100A12 expression was significantly upregulated in patients with sepsis and SIMD (|log2 FC| > 2, adjusted p < 0.05)." (PMID 40926894, 2025). "Unexpectedly, the prognosis of sepsis was significantly associated with four of the five hub genes: HK3, GPR84, CLEC4D, and S100A12." (PMID 40821971, 2025). "Bioinformatics analysis showed upregulation of S100A12 in sepsis and SIMD, enriched in multiple inflammation-related pathways." (PMID 40926894, 2025). "This study performed differential expression analysis using datasets from GEO to evaluate changes in S100A12 expression in sepsis and sepsis-induced myocardial dysfunction (SIMD), followed by GO and KEGG pathway enrichment analyses." (PMID 40926894, 2025). "This study combined bioinformatics analysis with clinical validation and found that S100A12 was persistently elevated in patients with sepsis and SIMD." (PMID 40926894, 2025). "In contrast, the mechanistic role of S100A12 in sepsis immune regulation is more clearly defined, meriting further in-depth investigation of its clinical translational potential as a diagnostic biomarker and potential therapeutic target." (PMID 41305822, 2025). "Ultimately, intersecting the “MEgreen” module related to sepsis and the “MEgrey” module associated with AF with their respective up-regulated genes highlighted S100A12 as the core shared gene between sepsis and AF." (PMID 39444551, 2024). "This implies S100A12's involvement in new-onset AF's pathogenesis in sepsis, marking it as a critical regulatory gene." (PMID 39444551, 2024). "We also discovered potential small molecule drugs targeting S100A12 for treating new-onset AF in sepsis." (PMID 39444551, 2024). "Serum levels of S100A12 were induced in patients with bacterial infections and patients with sepsis." (PMID 39066246, 2024). "balsalazide, methandriol, olopatadine and tibolone, pinpointed as prospective treatments targeting S100A12 for sepsis-related AF." (PMID 39444551, 2024). "We identified S100A12 as a key gene influencing the new-onset AF in sepsis through immune regulation, presenting considerable diagnostic and predictive value." (PMID 39444551, 2024). "Exploring the potential for small molecule drugs to treat new-onset AF in sepsis, we utilized the cMAP database to identify small molecules highly similar to S100A12 gene loci by enrichment score." (PMID 39444551, 2024).
Sepsis (continued). "Elisa results demonstrated a significant increase in both inflammatory markers and S100A12 expression in the serum of mice with acute sepsis; however, treatment with amlexanox was able to suppress the inflammatory response and reduce S100A12 expression." (PMID 39444551, 2024). "In animal studies, acute sepsis increased S100A12 expression in serum and atrial tissues, correlating positively with inflammatory markers (IL-1β, IL-6, TNF-α) and negatively with heart rate, indicating a predisposition to AF." (PMID 39444551, 2024). "In sepsis, S100A12 expression level was negatively correlated with the abundance of memory B cells (r = −0.213, P < 0.01), activated dendritic cells (r = −0.214, P < 0.01), resting NK cells (r = −0.179, P < 0.05) and CD8T cells (r = −0.263, P < 0.001)." (PMID 39444551, 2024). "Secondly, the exact mechanisms by which S100A12 influences the development of new-onset AF in sepsis warrant further exploration." (PMID 39444551, 2024). "As an additional comparison, S100A12 expression was above 8.0 in 39 of the 42 sepsis patients (92.9%, median value 10.23), while IFI27 expression was above 4.5 in only 10 of these 42 sepsis patients (23.8%, median value 1.94)." (PMID 36649304, 2023). "Another study reported that S100A12 promoted inflammation in sepsis-induced acute respiratory distress syndrome by activating the NLRP3 inflammasome signaling pathway." (PMID 37671148, 2023). "Expression of three biomarkers (IRAK3, RNASE2, S100A12) was visualized in both HC and sepsis samples." (PMID 38332910, 2023). "S100A12 expression increases during sepsis, and its expression is known to be released from granulocytes in vitro and in vivo by an inflammatory challenge." (PMID 36979757, 2023). "Recently, it has been described that calprotectin can be measured in the saliva of pigs showing increases in experimentally induced sepsis, as well as the increases in calprotectin and S100A12 in saliva in pigs with meningitis due to Streptococcus suis." (PMID 37627347, 2023). "Through probable receptor competition, inhibition of S100A12 increased IL-10 production in LPS-stimulated PBMCs from both controls and patients with sepsis." (PMID 35723375, 2022). "Day one plasma soluble RAGE (sRAGE) and S100A12 levels in patients with sepsis were significantly higher than those in controls (2481.3 ± 295.0 vs. 1273.0 ± 108.2 pg/mL, p < 0.001; 530.3 ± 18.2 vs. 310.1 ± 28.1 pg/mL, p < 0.001, respectively)." (PMID 35723375, 2022). "We measured plasma S100A12 levels and cytokine responses (mean ± standard error mean) of lipopolysaccharide (LPS)-stimulated peripheral blood mononuclear cells (PBMCs) after S100A12 inhibition in healthy controls and patients with sepsis on days one and seven." (PMID 35723375, 2022). "Compared with healthy volunteers, patients and neonates with sepsis display increased circulating S100A12 levels." (PMID 35723375, 2022). "Day 1 plasma levels of sRAGE and S100A12 in patients with sepsis were significantly higher than those in controls." (PMID 35723375, 2022). "The S100A12 expression was further elevated in the sepsis group compared to the uncomplicated infection group (p = 0.0074), where 16 of the 39 sepsis patients (41%) had higher S100A12 expression than the highest value in the uncomplicated infection group." (PMID 34108608, 2021). "It was evident that S100A12 expression was significantly elevated in the mild sepsis group compared to the SIRS group (p = 0.027), further validating S100A12 as a marker for infection." (PMID 34108608, 2021). "The S100A12 expression was further elevated in the severe sepsis group compared to the mild sepsis group (p = 0.042)." (PMID 34108608, 2021). "First, using RNA-Seq data from three independent studies on sepsis, I demonstrated that S100A12 was a marker for sepsis and severity of sepsis." (PMID 34108608, 2021). "It has been reported that another member of the S100 family, S100A12, promotes sepsis-induced ARDS via activating the NLRP3 pathway." (PMID 33549095, 2021).
Sepsis (continued). "Previously, it was demonstrated that HMGB1 and S100A12 are released in patients with severe sepsis and HMGB1 in mice with experimentally induced abdominal sepsis." (PMID 26824892, 2016). "Several known MDSC-associated genes were highly up regulated in breast cancer/sepsis monocytes when compared with healthy controls, including e.g. ARG1 and S100A12." (PMID 25992611, 2015). "S100A12, a pro-inflammatory calcium-binding protein, may contribute to sepsis-induced renal injury through oxidative and immune-mediated mechanisms." (PMID 41572197, 2026). "Screening identified 70 upregulated and 762 downregulated neutrophil-associated genes, which were intersected with differentially expressed genes (DEGs) between healthy controls and sepsis patients, yielding 13 overlapping genes – including S100A12 – as potential drivers." (PMID 41305822, 2025). "Moreover, S100A12 has been found to induce inflammation and apoptosis in septicemia-induced ARDS by activating the NLRP3 inflammasome signaling pathway." (PMID 40655156, 2025). "Although S100A12 has been extensively investigated in other cardiac conditions such as heart failure, Kawasaki disease, and myocardial infarction, studies specifically addressing its role in sepsis-induced myocardial dysfunction (SIMD) are scarce." (PMID 40926894, 2025). "The MRP-126 gene found in reptiles and birds is an orthologue to mammalian S100-A12 belonging to the S100/calgranulin family of proteins and S100-A12 is considered a pro-inflammatory modulator used as a biomarker of cellular damage, trauma and sepsis in mammals." (PMID 40823445, 2025). "In addition, S100A12, the neutrophil activation marker protein with increased serum level in sepsis patients, exhibits a PMA-specific release pattern from neutrophils." (PMID 41033464, 2025). "By using an acute sepsis mouse model, we further established S100A12 as a key gene for new-onset AF in sepsis and examined amlexanox's impact on the S100A12 gene in treating this condition, underscoring S100A12's role in augmenting AF risk through inflammation promotion." (PMID 39444551, 2024). "Experimental validation showed increased S100A12 expression in the serum and atrial tissue of mice with acute sepsis, with a positive correlation between serum S100A12 expression and inflammatory markers, suggesting S100A12's potential as a biomarker for predicting inflammatory response." (PMID 39444551, 2024). "Previous studies have demonstrated that S100A12 enhances the expression of adhesion factors and induces the activation of human monocytes via Toll-like receptor 4, thereby acting as an enhancer of innate immunity in the early stages of inflammation and sepsis." (PMID 38238762, 2024). "Furthermore, TF-gene interaction networks for S100A12 and related genes in sepsis and AF were constructed." (PMID 39444551, 2024). "This study confirmed S100A12 elevation in new-onset AF in sepsis." (PMID 39444551, 2024). "Notably, amlexanox, by targeting S100A12 emerges as the most clinical relevant intervention for managing new-onset AF in sepsis patients." (PMID 39444551, 2024). "S100A12 expression was positively correlated with the abundance of naive B cells (r = 0.266, P < 0.001), eosinophils (r = 0.379, P < 0.001), M0 macrophages (r = 0.586, P < 0.001), M1 macrophages (r = 0.287, P < 0.001) and Tregs (r = 0.159, P < 0.05) in sepsis." (PMID 39444551, 2024). "Firstly, S100A12 has been identified as a key molecule, playing a crucial role in the immune and inflammatory responses in IE patients, while primarily released at the infection site in sepsis patients." (PMID 38332910, 2023). "S100A12, a marker of inflammation in severe sepsis, was dramatically augmented in IR_cluster2 patients, further indicating that IR_cluster2 patients may develop pulmonary injury and endure severe disease burden." (PMID 37932287, 2023).
Sepsis (continued). "Furthermore, a previous study suggested that S100A12 is a biomarker of pulmonary damage involved in the pathogenesis of sepsis-induced ARDS54–56." (PMID 37932287, 2023). "Additionally, by comparing the expression profiles between disease samples and control samples, it was found that the expression levels of CD177, RNASE2, IRAK3, and S100A12 were significantly elevated in both IE and sepsis samples." (PMID 38332910, 2023). "Therefore, this prospective observational study was designed using repeated blood sampling to determine the role of S100A12 in patients with sepsis." (PMID 35723375, 2022). "More studies are needed to clarify the role of S100A12 in sepsis-induced AKI." (PMID 36143874, 2022). "This study found that patients with sepsis had higher plasma S100A12 levels than the controls." (PMID 35723375, 2022). "First, I examined whether S100A12 expression can be a marker for severe infection especially sepsis." (PMID 34108608, 2021). "First, it was demonstrated that S100A12 was a marker for sepsis and severity of sepsis." (PMID 34108608, 2021). "S100A12 could promote inflammation and cell apoptosis in sepsis-induced ARDS while inhibiting fibroblast migration via the receptor for advanced glycation end products." (PMID 34368225, 2021). "S100A12 is overexpressed during inflammation and might serve as a general marker of inflammatory diseases, as well as one of the markers of sepsis immunosuppression through endotoxin tolerance." (PMID 32479514, 2020). "Finally, SHAP analysis highlighted S100A12 as a pivotal biomarker for sepsis." (PMID 41305822, 2025). "Our findings in SIMD are consistent with these observations, suggesting that S100A12 may represent a shared inflammatory mediator across different cardiac pathologies, while also highlighting its potential as a specific biomarker for sepsis-related myocardial dysfunction." (PMID 40926894, 2025). "Furthermore, our mediating analysis revealed that effector memory T-cells (CD45RA- CD28- CD8br) could reduce the protein levels of S100A12, thereby exacerbating the severity of sepsis." (PMID 39076981, 2024). "Interestingly, we found that both sepsis and septic shock patients with higher expression of S100A12 also have a higher neutrophil count, a cell type whose immune role is well documented due to its proficiency in bacterial clearance through phagocytic mechanisms." (PMID 38892107, 2024). "Therefore, activation of S100A12 could be even stronger in sepsis, but it was infrequently accompanied by the activation of IFI27 (except for viral sepsis)." (PMID 36649304, 2023). "S100A8/A9 (also known as calprotectin) and S100A12 (also known as calgranulin C) are considered biomarkers of potential interest and are proteins members of the calgranulin family which is related to different inflammatory conditions, immune-mediated diseases, and sepsis." (PMID 37627347, 2023). "Therefore, S100A12 plays an important role in sepsis pathogenesis." (PMID 35723375, 2022). "Therefore, S100A12 expression is an indicator of severity in sepsis." (PMID 34108608, 2021). "Thus, S100A12 expression is an indicator of treatment progress in sepsis." (PMID 34108608, 2021). "The next question is whether S100A12 expression is correlated with sepsis severity." (PMID 34108608, 2021). "This study identified four hub genes (CLEC4D, GPR84, S100A12, and HK3) with significant prognostic value in sepsis and predicted a ceRNA network (NEAT1-hsa-miR-495-3p-ELF1) regulating their expression." (PMID 40821971, 2025). "Therefore, S100A12 may serves as a linchpin in the accurate identification of sepsis." (PMID 41305822, 2025). "Our findings showed that the expression of RETN, S100A12, IL18R1, and KL was higher in the sepsis group, while the expression of GZMB, HLA-DPA1, CD3E, IL2RB, CD3G, and CCR3 was higher in the control group." (PMID 38124071, 2023).
Sepsis (continued). "The research indicated that expression of S100A12 and S100A9 in the peripheral blood of sepsis patients was upregulated compared with that of healthy controls, which was consistent with our results." (PMID 37671148, 2023). "We successfully identified four key biomarkers correlated with IE and Sepsis, namely CD177, IRAK3, RNASE2, and S100A12." (PMID 38332910, 2023). "In the case of bacterial induced sepsis patients, a possible activation of the NLRP3 inflammasome pathway, which has been shown to be involved in the effect of S100A12 on the pathogenesis of sepsis-induced ARDS, was revealed." (PMID 36979757, 2023). "As shown in these figures, the expression levels of RETN, S100A12, IL18R1, and KL were higher in the sepsis group, while that of GZMB, HLA-DPA1, CD3E, IL2RB, CD3G, and CCR3 were higher in the normal group (p < 0.05)." (PMID 38124071, 2023). "And many of these genes (such as CD177, S100A12, and CLEC4D) played a critical role in sepsis pathology." (PMID 35739592, 2022). "Our study is the first to demonstrate that inhibiting S100A12 with neutralizing anti-S100A12 human antibody significantly increased TNF-α and IL-10 production in LPS-stimulated PBMCs from controls and patients with sepsis." (PMID 35723375, 2022). "Another marker of sepsis in both neonates and adults that was up-regulated here is S100A12 (also called calgranulin C), which is an alarmin involved in regulating innate immune/inflammatory responses." (PMID 32479514, 2020). "Another notable pathway expressed at higher levels in sepsis survivors related to the receptor for advanced glycation endproducts (RAGE) pathway and included the RAGE-related genes S100A8, S100A9, S100A12, and formyl peptide receptor 1 (FPR1)." (PMID 25538794, 2014). "Among these, we found certain S100 family proteins (i.e. S100A12 and S100A11) exclusively elevated in sepsis samples, while traditional pro-inflammatory S100A8 and S100A9 were similarly expressed in both healthy and sepsis samples." (PMID 40965975, 2025). "Salivary levels for ITIH4 (Pig major acute phase protein, Pig-Map) and S100A8/A9 and S100A12 after stress, sepsis, and non-septic inflammation have been measured recently." (PMID 41199397, 2025). "Finally, we validated the expression of core hub genes (excluding S100A12) in the two mouse models using qRT-PCR, identifying SOCS3 as a potential key biomarker of sepsis-induced liver injury." (PMID 40808951, 2025). "First, the biological mechanisms of S100A12 in sepsis have not been validated via in vitro or in vivo experiments; its immunoregulatory roles warrant further validation using animal models or serum samples, a priority for our subsequent research phase." (PMID 41305822, 2025). "A recent research demonstrated that human S100A12 was an endogenous TLR4 ligand that induces monocyte activation, thereby acting as an amplifier of innate immunity during early inflammation and the development of sepsis." (PMID 39076981, 2024). "Serum S100A12 levels are increased in infectious and non-infectious inflammatory diseases such as inflammatory bowel disease, rheumatoid arthritis, sepsis and community-acquired pneumonia." (PMID 39066246, 2024). "In a cross-sectional study enrolling patients without sepsis, serum S100A12 and HMGB1 levels were elevated in patients with AKI compared to those in patients on hemodialysis." (PMID 36143874, 2022). "Similarly, the genes screened by WGCNA such as CD177, S100A12, and CLEC4D have also been described to be important in the pathogenesis of sepsis." (PMID 35739592, 2022). "S100A12, a pro-inflammatory factor, can promote inflammation and cell apoptosis in ARDS induced by sepsis through activating the NLRP3 inflammasome signaling pathway, which is a potential biomarker of pulmonary injuries in the clinical diagnosis of ARDS induced by sepsis." (PMID 34393665, 2021). "The plasma levels of AGE, HMGB1, and S100A12 did not change in patients with sepsis after 6 d." (PMID 35723375, 2022).